SOX2 (SRY-box transcription factor 2)
Diseases named in the same sentence as SOX2 in open-access papers (continued):
Sharing a sentence is not in itself a finding about the gene and the disease.
Anophthalmia (52 papers, 2007 to 2025). Absence of the globe or eyeball. "In severe bilateral cases of anophthalmia and microphthalmia, a genetic cause has been identified in approximately 80% of cases, with de novo heterozygous loss-of-function point mutations in SOX2 being the most common, accounting for 10–20% of cases." (PMID 40038803, 2025). "Mutations in SOX2 are associated with severe ocular malformations, particularly bilateral anophthalmia and microphthalmia, with about 10% of cases due to SOX2 haploinsufficiency." (PMID 41303332, 2025). "Key genetic contributors to bilateral anophthalmia include de novo, heterozygous, loss-of-function mutations in SOX2 or OTX2, which regulate crucial eye development pathways such as optic vesicle formation and forebrain specification." (PMID 40843047, 2025). "SOX2-associated ocular malformations, including anophthalmia, microphthalmia, sclerocornea, cataracts, persistent hyperplastic primary vitreous and optic disc dysplasia, are variable in type but are most often bilateral and severe." (PMID 40038803, 2025). "Previous research has linked mutations in genes such as CHX10, MAF, PAX6, PAX2, RX (RAX), SHH, SIX3, OTX2, and SOX2 to phenotypes associated with microphthalmia, anophthalmia, and coloboma (MAC)." (PMID 39129019, 2024). "Heterozygous SOX2 loss-of-function leads to anophthalmia/microphthalmia syndrome (OMIM 206900) that almost always includes NDD, sometimes without ocular abnormalities." (PMID 38300321, 2024). "This is based on two observations: in humans, heterozygous SOX2 mutations are linked with the anophthalmia–esophageal–genital syndrome; in mice, hypomorphic Sox2 alleles display similar phenotypes in the eye and EA/TEF." (PMID 37738673, 2023). "Pathogenic mutations in the SOX2 gene (encoding the SRY-related HMG-box 2 transcription factor protein) were initially identified as a monogenic cause for anophthalmia/microphthalmia (A/M)." (PMID 36602867, 2023). "SOX2 is a single exon transcription factor previously associated with anophthalmia, microphthalmia, and coloboma." (PMID 35148715, 2022). "Previously, 21 of 37 patients with anophthalmia and microphthalmia carried frameshift and deletion/translocation mutations in the SOX2 gene." (PMID 35148715, 2022). "SOX2 intragenic variants and deletions are the most common cause of anophthalmia/microphthalmia, typically syndromic with commonly seen esophageal, genitourinary, and neurological anomalies." (PMID 35885948, 2022). "Mutations in the SOX2 gene are known to account for 20% of anophthalmia and microphthalmia in humans, but markers in proximity to the SOX2 gene and within its regulator, SOX2-OT, have recently been associated with cataract." (PMID 35749127, 2022). "Among the last, pathogenic variants in the transcription factor gene SOX2 have been reported as causative in 10–20% of the individuals with anophthalmia or severe microphthalmia, and in up to 40% of those affected bilaterally." (PMID 33719903, 2021). "Consistent with SOX2′s known role in microphthalmia and anophthalmia in human patients, knockdown and knockout Rbm24-deficient mice and zebrafish often displayed eye defects including microphthalmia and/or anophthalmia." (PMID 33494192, 2021). "Mutations in SRY (sex determining region Y)-box2 (SOX2) account for approximately 20% of human anophthalmia cases." (PMID 33494192, 2021). "The major single-gene SOX2 variant was found in a fetus with bilateral anophthalmia, which accounted for 10–15% of all anophthalmia and microphthalmia cases." (PMID 34367232, 2021). "The SOX2 deletion found in the proband is the most commonly reported variant in this gene, accounting for up to 20% of SOX2-related occurrences of anophthalmia." (PMID 33719903, 2021). "For example, loss-of-function variants in SOX2 are known to cause anophthalmia and microphthalmia in addition to other phenotypes such as developmental delay and structural brain anomalies." (PMID 30837331, 2019).
Anophthalmia (continued). "Mutations in human SOX2 lead to anophthalmia, but most mutations are de novo mutations, which appear in the parental germline, and most of the affected persons are sterile." (PMID 30919050, 2019). "In humans, the genetic cause for anophthalmia (and severe microphthalmia) can be identified in ~ 80% of cases because of mutations in SOX2 or OTX2." (PMID 30919050, 2019). "Anophthalmia, the most severe phenotype, is associated with mutations of the Rax, Sox2, Lhx2, BMP-4, and BMP7 genes." (PMID 31817535, 2019). "Heterozygous variants of sex-determining region Y-box 2 (SOX2) are the most common known cause of bilateral anophthalmia and severe microphthalmia, accounting for 15%–40% of cases." (PMID 31416264, 2019). "SOX2 mutations are the major single-gene cause of anophthalmia and microphthalmia, accounting for ~ 10–15% of all cases." (PMID 30200890, 2018). "In a previous study, we screened SOX2 for mutations in the affected patient, this gene being the most frequent molecular cause of severe bilateral eye malformations, such as anophthalmia." (PMID 29178648, 2017). "Among them including Sox2, Otx2, Pax6, have been associated with anophthalmia and microphthalmia in many individuals." (PMID 27494603, 2016). "A novel D123G mutation in the C-terminal tail following the Sox2 HMG domain was detected in this family that was attributed to anophthalmia." (PMID 25578969, 2015). "A study recruited 10 patients aged from 2 to 9 years screening for gene mutation found that Sox2 mutation is genetically correlated with inherited ocular phenotypes, anophthalmia and microphthalmia." (PMID 25051057, 2014). "Heterozygous mutations in the Sox2 gene have been linked to eye malformations like anophthalmia and microphthalmia." (PMID 25111779, 2014). "SOX2 heterozygous loss-of-function (het-LOF) mutations are associated with a syndromic form of anophthalmia or severe microphthalmia." (PMID 24363063, 2014). "Aniridia, anophthalmia and microphthalmia have been associated with haploinsufficiency of SOX2 while anterior eye defects, including defects of the iris and ciliary body have been associated with haploinsufficiency of PAX6 in humans." (PMID 25111779, 2014). "A SOX2 missense mutation, c.368A>G p.(Asp123Gly), in one child with anophthalmia/microphthalmia that was inherited from her mother, who has bilateral chorio-retinal coloboma and microcornea in one eye." (PMID 24498598, 2013). "A screen for heterozygous loss-of-function mutations in either SOX2 or OTX2 should clearly be the first line test that will have a significant detection rate in cases of anophthalmia." (PMID 24498598, 2013). "On the other hand, loss-of-function mutations in SOX2 produce syndromes characterized by anophthalmia and hypopituitarism." (PMID 23217425, 2012). "One such gene is SOX2, located in 3q26.3-q27, mutations in which have been shown to cause anophthalmia and microphthalmia in association with other variable forebrain abnormalities." (PMID 21738392, 2011). "SOX2 is a High Mobility Group (HMG) DNA binding domain-containing transcription factor with a well established role as a common cause of dominant anophthalmia/microphthalmia (A/M)." (PMID 20454695, 2010). "The anophthalmia/microphthalmia phenotype in patients with SOX2 mutations can be bilateral, unilateral, or, occasionally, absent; 14 of the 71 individuals reviewed previously or subsequently reported do not have anophthalmia/microphthalmia of either eye." (PMID 20454695, 2010). "Expression of Sox2 is observed in mouse and human eye lens; in humans, heterozygous loss-of-SOX2 function causes several defects including bilateral anophthalmia, and defects in the hypothalamo-pituitary-gonadal axis." (PMID 21103067, 2010). "Although the relationship between the mutation at the 3′-UTR and anophthalmia/ microphthalmia is indeterminate, one possibility is that the nucleotide substitution at c.*557G>A affects SOX2 expression." (PMID 18385794, 2008).
Anophthalmia (continued). "The present study identified two novel mutations and two sequence variants (one novel, one known SNP) in SOX2 in 6 (two siblings) out of 34 anophthalmia/microphthalmia/ coloboma patients." (PMID 18385794, 2008). "The frequency of mutations in SOX2 in anophthalmia and microphthalmia patients is estimated at 10% for this study, which is consistent with previous reports." (PMID 18385794, 2008). "Previously reported cases of anophthalmia and microphthalmia were associated with SOX2 whole-gene deletions or coding sequence mutations." (PMID 18385794, 2008). "This confirms the importance of SOX2 mutation screening in patients with anophthalmia/microphthalmia." (PMID 18385794, 2008). "This suggests that SOX2 mutations cause a more severe disruption of normal eye development and that microphthalmia/anophthalmia are of a spectrum of the same disease." (PMID 18385794, 2008). "As expected with genes expressed in the developing brain, patients with inherited PAX6 and SOX2 mutations exhibit CNS malformations in addition to dominantly inherited anophthalmia/microphthalmia." (PMID 18039390, 2007). "Among IHH-ascertained cases, ocular phenotypes were variable for both PTVs and missense alleles, with patients harboring SOX2 PTVs demonstrating severe ocular defects, including right amblyopia, strabismus, blindness, and bilateral anophthalmia (cases 1 and 2)." (PMID 36602867, 2023). "Moreover, it points to the fact that microphthalmia in Tmem107−/− animals is likely caused by down-regulated Pax6, whereas anophthalmia is rather caused by altered expression of Sox2." (PMID 37863656, 2023). "PAX6 and SOX2 are transcription factors associated with anophthalmia and microphthalmia in humans." (PMID 37863656, 2023). "With regard to SOX2, the clinical features associated with SOX2 mutations include eye disorders (anophthalmia and microphthalmia), brain malformations (usually hippocampal), esophageal atresia, genital abnormalities, hypoplastic anterior pituitary and intellectual disabilities." (PMID 33878729, 2021). "Anophthalmia can occur as a unique clinical feature, although in one-third of cases it is associated to genetic syndromes, such as the Wolf-Hirschhorn or mutations of the SOX2 or PAX6 genes." (PMID 28673238, 2017). "In humans, SOX2-associated anophthalmia is a haploinsufficiency disease." (PMID 24498133, 2014). "Patients with heterozygous loss-of-function mutations in SOX2 exhibit anophthalmia or microphthalmia and some cases have additional neural phenotypes including learning difficulties, specific motor and brain abnormalities, seizures and anterior pituitary hypoplasia." (PMID 24498133, 2014). "Sox2 also seems to play a causative role in isolated anophthalmia and microphthalmia." (PMID 21806818, 2011). "Heterozygous mutations in SRY-box 2 (SOX2) account for approximately 10% of anophthalmias." (PMID 21203406, 2010). "Mutations in SOX2 account for approximately 10% of anophthalmia and microphthalmia cases." (PMID 18385794, 2008). "SOX2 mutations cause anophthalmia (OMIM 184429) and brain malformations." (PMID 18334927, 2008). "Similarly, genetic screening in Mexican patients with anophthalmia/microphthalmia has allowed the expansion of the phenotypic spectrum resulting from mutations in major ocular genes, as observed in subjects carrying SOX2 deleterious variants and dental anomalies." (PMID 41480153, 2025). "Similarly, two daughters, anophthalmia and microphthalmia in one and BA in the other associated with partial agenesis of the corpus callosum, were born to a phenotypically normal mother who carries the same SOX2 deletion in a mosaic state." (PMID 24498598, 2013). "Interestingly, the identified SOX2 variant, c.70_89del, is a recurrent variant now reported in 20 individuals; while the majority of cases presented with a severe phenotype of syndromic anophthalmia/microphthalmia, phenotypic variability has been reported in some cases." (PMID 35885948, 2022).
Anophthalmia (continued). "Although SOX2 in anophthalmia, persistent hyperplastic primary vitreous in NDP, and micrognathia in BMP2 were detected in this study, up to 60% of cases with underlying genetic causes remained undetermined." (PMID 34367232, 2021). "Single-gene deletions and mutations affecting the ability to produce proteins and enzymes such as SOX2, MFRP, ALDH1A3, STRA6, PAX2, and OTX2, have been identified as causing isolated microphthalmia and anophthalmia and syndromic forms." (PMID 30153864, 2018). "A heterozygous inactivation of SOX2 causes syndromic microphthalmia-3 (MCOPS3), a genetic disease characterized by anophthalmia, microphthalmia mild hypopituitarism, and sometimes learning difficulties, convulsions, motor dysfunctions, and growth problems." (PMID 27822457, 2016). "SOX2 is to date the gene most frequently involved in anophthalmia and accounts for up to 10% of cases." (PMID 22736936, 2012). "Mutations in the SOX2 and CHX10 genes have been reported in patients with anophthalmia and/or microphthalmia." (PMID 18385794, 2008). "Although PAX6 mutations are an extremely rare cause of anophthalmia, there has recently been interest in a possible co-operative role between PAX6 and SOX2." (PMID 18039390, 2007). "Recently, via ‘genotype-first’ approaches, loss-of-function SOX2 variants have been found in people with developmental delay but without anophthalmia or microphthalmia, broadening the phenotypic spectrum associated with this gene." (PMID 30837331, 2019). "Humans with mutations in SOX2 often suffer from eye defects including anophthalmia (no eye) and microphthalmia (small eye)." (PMID 25488119, 2014). "Heterozygous mutations in human SOX2 are associated with anophthalmia (absent eye) and account for 10 to 20% of cases of severe bilateral ocular malformation, including microphthalmia (small eye) indicating a defect in OCPC proliferation or survival." (PMID 25488119, 2014). "Consistent with the absence of a significant paternal origin effect, SOX2 anophthalmia syndrome is characterized by a wide mutation spectrum." (PMID 22171155, 2011). "Mutations in SOX2 do not appear to be a common cause of ocular defects other than anophthalmia/microphthalmia." (PMID 20454695, 2010). "Only SOX2 has thus far been identified as a major anophthalmia/microphthalmia gene, with mutations primarily arising de novo." (PMID 18039390, 2007). "In conclusion, this study confirms that heterozygous loss of function mutations in SOX2 cause anophthalmia and microphthalmia and represent approximately 10% of patients ascertained for anophthalmia and microphthalmia but may also be non-penetrant." (PMID 18385794, 2008). "Disease-associated SOX2 variants have been inherited from asymptomatic parents as a result of mosaicism, such as a case of a mother with no ocular features who had a daughter with bilateral anophthalmia along with extraocular features of SOX2 syndrome as a result of germinal mosaicism." (PMID 31416264, 2019). "Herein we have set out to determine the parent of origin for one of the earliest anophthalmic disorders to be genetically defined, sex determining region Y (SRY)-box 2 (SOX2; OMIM 184429) anophthalmia syndrome." (PMID 22171155, 2011). "Seventy patients having non-syndromic forms of colobomatous microphthalmia (n=25), isolated microphthalmia (n=18), or anophthalmia (n=17), and syndromic forms of micro/anophthalmia (n=10) were included in this study after negative molecular screening for OTX2, RAX, SOX2, and CHX10 mutations." (PMID 21203406, 2010).
embryonal carcinoma (52 papers, 2010 to 2026). A non-seminomatous malignant germ cell tumor characterized by the presence of large germ cells with abundant cytoplasm resembling epithelial cells, geographic necrosis, high mitotic activity, and pseudoglandular and pseudopapillary structures formation. "SOX17, a marker of seminomatous identity, was consistently reduced, while SOX2, which is associated with pluripotency and embryonal carcinoma-like features, was upregulated or unchanged." (PMID 40649953, 2025). "Non‐seminomas, including embryonal carcinomas, are more prone to metastatic activity, and some retain pluripotency markers including OCT4, while embryonal carcinomas express SOX2, a transcription factor typically repressed in human primordial germ cells." (PMID 40693358, 2026). "It regulates stem cell markers such as POU5F1 (OCT4) and SOX2,50,51 associated with GCNIS and embryonal carcinoma." (PMID 39999848, 2025). "The oncogenic transformation of hPGCs into pluripotent embryonal carcinoma (EC) cells and germ cell tumours entails the loss of SOX17 and the gain of SOX2 function." (PMID 35411086, 2022). "As the target gene, SOX2 has been confirmed being repressed by NF‐YA to decrease the proliferation and pluripotency in embryonic carcinoma." (PMID 32954681, 2020). "Although comparative immunocytochemistry analysis revealed that MSCs from the umbilical cord are more likely to express SOX2, it is significantly lower than in embryonic carcinoma cells." (PMID 32192154, 2020). "SOX2 is a core component of the transcriptional network responsible for maintaining embryonal carcinoma cells (ECCs) in a pluripotent, undifferentiated state of self-renewal." (PMID 25156079, 2014). "F9 embryonic carcinoma cells were chosen, as they express Sox2 and Oct4, and have demonstrated both de novo methylation and demethylation of transgenes." (PMID 24324735, 2013). "Both fgf4 and utf1 are typical Sox2 target genes, therefore, we used two biotin-labeled DNA probes, covering the Sox2-binding sites in fgf4 and utf1 respectively, to enrich endogenous Sox2 from P19 embryonal carcinoma cells." (PMID 22046437, 2011). "SOX2 expression is also seen in embryonal carcinoma and teratoma components." (PMID 41018086, 2025). "In keeping with a restricted expression of RARγ within primitive cells, the binding sites for RAR/RXR dimers within undifferentiated F9 embryonal carcinoma cells coincided with loci that are targeted by transcription factors that are important to pluripotency (SOX2, NANOG, and POU5f1)." (PMID 37082619, 2023). "Moreover, data from TCGA showed that SOX2 was significantly overexpressed in embryonal carcinoma cells, while HDAC9 expression was increased in seminoma cells." (PMID 36713456, 2022). "Furthermore, overexpression of SOX2 inhibited the activity of OCT4 promotor in embryonal carcinoma cells." (PMID 26706028, 2015). "Human embryonic stem cells and human embryonal carcinoma cells have been studied extensively with respect to the transcription factors (OCT4, SOX2 and NANOG), epigenetic modulators and associated signalling pathways that either promote self-renewal or induce differentiation in these cells." (PMID 25369332, 2014). "As a result of treatment of 293T monolayer cells with embryonic carcinoma cell extract, spherical colonies of 293T cells develop and induce Oct4 gene expression which in turn induces the expression several Oct4-responsive genes like Sox2, Nanog and Rex1." (PMID 20615238, 2010). "An embryonic carcinoma cell line, NCCIT, was also examined as a positive control for SOX2 expression." (PMID 38334608, 2024). "NTERA-2 cells, a pluripotent human embryonic carcinoma cell line, were NANOG-, OCT4A- and SOX2-positive." (PMID 36900355, 2023). "OCT3/4, NANOG, SOX2, GP-3, and CD30 markers can help reliably differentiate yolk sac tumors and embryonal carcinomas." (PMID 37443818, 2023).